EGFR (epidermal growth factor receptor)
Diseases named in the same sentence as EGFR in open-access papers (continued):
Sharing a sentence is not in itself a finding about the gene and the disease.
pancreatic cancer (continued). "The humanised anti-epidermal growth factor receptor (EGFR) monoclonal antibody matuzumab (formerly EMD 72000) is active against pancreatic cancer in preclinical studies." (PMID 16622465, 2006). "In preclinical studies, matuzumab demonstrated activity in the PAXF546 xenograft model of human pancreatic cancer that expressed high levels of EGFR and demonstrated almost complete resistance to clinically available chemotherapeutic drugs." (PMID 16622465, 2006). "Encouraging findings have also been reported with the combination of gemcitabine and the anti-EGFR chimeric monoclonal antibody cetuximab in the first-line treatment of patients with advanced pancreatic cancer." (PMID 16622465, 2006). "Epidermal growth factor receptor expression in pancreatic cancer has been correlated with tumour aggressiveness." (PMID 16622465, 2006). "Regarding the benefits of EGFR-targeted therapy in the combined modality treatment using either irradiation or chemotherapy, it is increasingly becoming clear that EGFR-targeted therapy is an important novel strategy for the treatment of pancreatic cancers." (PMID 16219105, 2005). "The overexpression of EGFR has been demonstrated in a number of human tumor types, including head-and-neck cancers, colon cancer, breast cancer, gliomas, lung cancer and pancreatic cancer." (PMID 16219105, 2005). "The expression of key genes for MAPK/ERK signaling, EGFR, ERK1, ERK2, c-Jun, and c-Fos, was analyzed according to different variables to investigate associations between patients’ specific features and the predisposition to develop pancreatic cancer." (PMID 40305202, 2025). "In a preclinical murine model of PDAC, addition of Bevacizumab and cetuximab (epidermal growth factor receptor (EGFR) inhibitory antibody) with gemcitabine/FOLOFRINOX significantly reduced pancreatic tumour weight compared to mice treated with chemotherapy alone." (PMID 41561521, 2025). "EGFR-targeted therapies have been employed in pancreatic cancer management for years." (PMID 40689200, 2025). "EGFR has also been shown to be required for tumorigenesis in a K-Ras(G12D) pancreatic cancer model, and ablation of EGFR leads to ∼2-fold reduction of downstream levels of Ras-GTP and phosphorylated ERK (herein referring to ERK1 and ERK2, also known as MAPK3 and MAPK1, respectively)." (PMID 41132131, 2025). "Since TGFα acts as one of the ligands of the EGFR, and the pancreatic cancer cell lines expressed the receptor, we reasoned that coexpression of the EGFR could facilitate the antiproliferative action of the anti-TGFα ADCs." (PMID 40410803, 2025). "Additionally, CD133 physically interacts with the epidermal growth factor receptor (EGFR) in pancreatic cancer cells." (PMID 39980929, 2025). "Notably, EGFR tyrosine kinase inhibitors (TKIs) against EGFR activation have been approved to treat certain kinds of cancers, such as lung and pancreatic cancers." (PMID 39838173, 2025). "Regarding the mechanism of action, it was further found that the epidermal growth factor receptor (EGFR) expression in pancreatic cancer cells could be reduced by retinoids such as ATRA, which was reflected by inhibition of EGFR ligand-induced proliferation." (PMID 39850424, 2025). "Randall J. Kim and colleagues found that inhibition of EGFR/HER2 could enhance radiosensitivity in wild-type K-RAS pancreatic cancer." (PMID 40656957, 2025). "In addition, the regulatory role of EGFR-AKT on the signaling axis has been shown to inhibit pancreatic cancer progression." (PMID 40391080, 2025). "Epidermal growth factor receptor (EGFR) is mostly over‐expressed in pancreatic cancer progression." (PMID 39434498, 2025). "Three cancer‐correlated biomarkers (epidermal growth factor receptor (EGFR), one pancreatic cancer marker (glypican‐1, GPC1) and macrophage migration inhibitory factor (MIF)) can be detected by the developed MAIP‐based platform with a detection limit as low as 5 pg mL−1." (PMID 40598854, 2025).
pancreatic cancer (continued). "Although AZD8055 was initially able to inhibit the activity of mTOR complexes 1/2 and the Akt signaling pathway, this inhibition was only transient; pancreatic cancer cells rapidly regained tolerance to the drug with the activation of EGFR and its downstream kinases." (PMID 40125551, 2025). "For pancreatic cancer, although monoclonal antibodies targeting integrin α3, Mucins, EGFR, TROP2 and α6β4 have demonstrated efficacy in pancreatic tumor xenograft models, their clinical translation has been limited with minimal survival benefits observed in patients." (PMID 38554200, 2024). "Based on data that has attributed cellular functions to fibroblast proliferation in other tissues, we investigated a panel of ten central regulators of cell proliferation (c-Myc, Cyclin D1, Cyclin E1, FGF2, FGFR2, EGFR, EGF, FGF1, FGFR1 and VEGFA) in pancreatic cancer-associated fibroblasts (CAFs)." (PMID 38678032, 2024). "The c-ERBB-1 proto-oncogene encodes EGFR, and while in the normal pancreas, c-ERBB-1 is expressed exclusively in the islets of Langerhans, human pancreatic cancer cell lines frequently demonstrate its overexpression, which is observed in up to 85% of ductal adenocarcinomas." (PMID 39087024, 2024). "Most patients with pancreatic cancer will have overexpression of EGFR." (PMID 39744013, 2024). "Clinically, CSI is applied as an adjuvant cancer therapy not a single compound, with our findings demonstrating that CSI-derived bufadienolides notably suppress pancreatic cancer cell proliferation by inducing G2/M arrest, potentially via the p-EGFR/KRAS/p-ERK1/2 pathway." (PMID 39770538, 2024). "Additionally, both in vitro and in vivo, the combination of alantolactone and an EGFR inhibitor such as erlotinib or afatinib showed a remarkable combinatorial anticancer effect against pancreatic cancer cells." (PMID 38397437, 2024). "With a goal to investigate the chronotherapeutic potential of a targeted agent based on our transcriptome data, we evaluated temporal cell viability after treatment with erlotinib, an EGFR inhibitor that is used to inhibit cell replication by targeting EGFR in pancreatic cancer." (PMID 38716727, 2024). "In our study, we found that silencing of HHLA2 can inhibit the EMT process of pancreatic cancer cells, and the mechanism may be related to the regulation of EGFR/MAPK /mTOR/AKT/ERK1/2 signaling pathway." (PMID 38762741, 2024). "Network pharmacology results suggest that kaempferol-sensitizes pancreatic cancer cells to ERL treatment, and that this effcet may be associated with the PI3K/AKT signaling pathway and EGFR-TKI resistance." (PMID 38324023, 2024). "Similarly, EGFR (epidermal growth factor receptor) inhibitors are very well explored for the treatment of several cancers, including colorectal, head and neck, lung, and pancreatic cancer." (PMID 38431714, 2024). "Overexpression of EGFR is found in up to 90% of pancreatic tumors." (PMID 39744013, 2024). "Erlotinib(ERL) is an EGFR tyrosine kinase inhibitor (TKI) used to treat pancreatic cancer." (PMID 38324023, 2024). "While the EGFRxHER2 heterodimer T-BsAb could ablate EGFR+HER2+ double-positive pancreatic tumors, deletion of either EGFR or HER2 completely abrogated antitumor efficacy." (PMID 38650005, 2024). "The increased expression of transforming growth factor-α (TGF-α) in the nerves surrounding the pancreas and epidermal growth factor receptor (EGFR) in pancreatic cancer cells were shown to increase the affinity of nerves for pancreatic cancer cells and vice versa." (PMID 38541624, 2024). "Indeed, the abundance of EGFR on the surface of cultured Wnt ligand–dependent pancreatic cancer cell lines HPAF-II and AsPC-1 increased significantly following Wnt inhibition." (PMID 38488003, 2024).
pancreatic cancer (continued). "In both in vivo (50, 100, 200 μM/L) and in vitro (4 mg/kg, for 30 days) studies, crocetin exhibited inhibitory effects on cell proliferation in pancreatic cancer cells by significantly modifying the expression of Cdc-2, Cdc-25C, Cyclin-B1, and epidermal growth factor receptor." (PMID 38419885, 2024). "Indeed, it was recently reported that SK2 activity promoted cell migration and invasion in pancreatic cancer cells by enhancing an integrin–EGFR–AKT (Protein kinase B) pathway." (PMID 38480668, 2024). "Interestingly, high integrin α6β4 in pancreatic cancer cells is associated with transcriptional upregulation of EGFR ligands, including EREG, which activates EGFR signalling and enhances cell motility and migration." (PMID 38687323, 2024). "However, the involvement of EGFR in CMG2-coordinated biological activities in pancreatic cancer cells and corresponding therapeutic opportunities are yet to dissected and evaluated." (PMID 39199664, 2024). "Thus, Magadala and Amiji made the first attempt to introduce the epidermal growth factor receptor (EGFR) recognition sequence into a gelatin base to study gene delivery to pancreatic cancer cells." (PMID 36834993, 2023). "In addition, CD147 promotes pancreatic cancer cell invasion by upregulating the EGFR/STAT3 signaling pathway." (PMID 37298389, 2023). "HER2 overexpression is seen in 4–50% of pancreatic cancer cases, and like EGFR, its role in predicting prognosis also remains unclear." (PMID 37179357, 2023). "Finally, we demonstrate that knockdown of NSD3 alters H3K36me2 methylation, downstream gene expression and EGFR/ERK signaling in pancreatic cancer cells." (PMID 37062069, 2023). "Interestingly, HER3 was found to preferentially dimerize with EGFR to induce cell proliferation, invasion, and migration in melanoma and pancreatic cancer." (PMID 37947595, 2023). "For example, epidermal growth factor expression and epidermal growth factor receptor transactivation may be induced by high glucose, which can contribute to promoting cell proliferation in pancreatic cancer." (PMID 36937438, 2023). "HER2 and HER3 are moderately expressed in pancreatic cancer, whilst EGFR is overexpressed." (PMID 37153618, 2023). "Notably, the expression of epidermal growth factor (EGF) and its receptor (EGFR) as prognostic factors are reported in certain pancreatic cancer patients." (PMID 37371811, 2023). "We complemented these analyses on murine DRG with the spatial transcriptome analysis of nerves within human pancreatic cancer specimens to explore whether we can detect the EGFR also in human nerves at the periphery that would bind TGF-α." (PMID 37607005, 2023). "Decorin is a small lysine-rich proteoglycan found in the extracellular matrix, that has been shown to inhibit tumour growth in many cancers, including pancreatic cancer, via interactions with the epidermal growth factor receptor and other members of the ErbB family." (PMID 37936126, 2023). "Furthermore, native human amniotic MSCs inhibit the proliferation of pancreatic cancer cells and promote apoptosis of pancreatic cancer cells by inhibiting the expression of EGFR, c-Src, and SGK223." (PMID 36834969, 2023). "Notably, the epidermal growth factor receptor (EGFR) is critical in inducing the EMT program in pancreatic cancer." (PMID 35892853, 2022). "Additionally, combination of alantolactone and an EGFR inhibitor, erlotinib or afatinib, demonstrated a remarkable synergistic anti-cancer effect against pancreatic cancer cells, further developed as a potential therapy for pancreatic cancer." (PMID 35684434, 2022). "The anti-EGFR monoclonal antibody nimotuzumab achieved a longer survival with a tolerable toxicity when added to gemcitabine (8.7 months vs. 6.1 months), in a recent phase II trial in patients with locally advanced pancreatic cancer." (PMID 36556296, 2022).
pancreatic cancer (continued). "The reason for exploring KRAS mutation status as a prognostic biomarker rather than any other potentially useful biomarkers, such as Ki67, is that these patients were being screened for potential inclusion in a clinical study of EGFR inhibition in KRAS wild-type pancreatic cancer." (PMID 36231137, 2022). "Previous studies have shown that more than 90% of pancreatic cancer cells presented epidermal growth factor receptor (EGFR) cell marker, and this marker is thought to be important as it is related to activation of cancer cell proliferation, angiogenesis, and cancer progression." (PMID 35745775, 2022). "Kmp in dosage-dependent manner prevents the pancreatic cancerous cells growth in PANC-1, MIA PaCa-2 and SNU213-pancreatic cancer cell line by causing apoptosis and efficiently preventing ERK-1/2, EGFR-related AKT and Src signalling pathways and migration of cells." (PMID 36557997, 2022). "A recent finding demonstrated that macropinocytosis could be specifically induced in a subset of pancreatic cancer cell lines with low intrinsic macropinocytic activity by glutamine depletion through the activation of EGFR–PAK signaling." (PMID 35177645, 2022). "Moreover, the Gem–E07 conjugate also showed a strong inhibition effect on growth of EGFR-positive pancreatic cancer cells after internalization through clathrin-mediated endocytosis." (PMID 36354547, 2022). "ROS-activated PKD1 stimulates transcription factors NF-κB1 and NF-κB2, which up-regulate the expression of EGFR and its ligands TGFα and EGF, thus inducing EGFR/KrasWT signaling cascade and, consequently, pancreatic cancer proliferation and malignant progression." (PMID 35805075, 2022). "Therefore, preventive or reactive treatment of skin rash caused by EGFR-TKI which improves the treatment compliance is essential to the patients with pancreatic cancer under EGFR-TKI treatment." (PMID 36165327, 2022). "In the past two decades, other than adjuvant chemotherapy treatment, such as folfirinox, and the combination of nab-paclitaxel with gemcitabine, only one additional drug has been approved to treat pancreatic cancer, namely, the epidermal growth factor receptor (EGFR) inhibitor erlotinib." (PMID 35740940, 2022). "Furthermore, ANO9 knockdown sensitises pancreatic cancer cells to EGFR-targeted treatment with erlotinib." (PMID 36497413, 2022). "Consequently, anti-EGFR antibodies have been functionalised with molecules to either monitor, target or kill, more specifically, pancreatic tumours." (PMID 35892707, 2022). "BCA101 (Bicara Therapeutics) is an EGFR/TGF-β fusion mAb; it is studied in phase I alone or in combination with the anti-PD1 pembrolizumab in patients with EGFR-driven advanced solid tumors including pancreas cancer with KRAS G12D mutation (NCT04429542)." (PMID 34451837, 2021). "This suggests that EGFR and MET are associated with the immune response in pancreatic cancer." (PMID 34479614, 2021). "Strikingly, the clinical response rate to ICI therapies remains unexpectedly poor inpatients with types of epithelial tumours that overexpress either wild-type (wt) or oncogenic alterations of the Epidermal Growth Factor Receptor (EGFR), such as lung, colon, prostate, or pancreas cancers." (PMID 35052732, 2021). "Thus, the inhibition of NETs/ IL‐1β/EGFR signalling is a new hope for targeted therapy of pancreatic cancer." (PMID 33955688, 2021). "A recent study has been reported that PRMT5 promotes EMT via EGFR in pancreatic cancer cells." (PMID 33495409, 2021). "In pancreatic cancer, miR-133a could exert the anticarcinogenic activity by directly targeting FSCN1, conversely, inhibition of miR-133a by LncRNA XIST could upregulate EGFR expression to accelerate PNI of pancreatic cancer." (PMID 34187567, 2021). "Here, we hope to provide new insights into the molecular mechanisms of pancreatic cancer, and may help facilitating development of EGFR-based therapies for human cancer." (PMID 33937024, 2021).
pancreatic cancer (continued). "Hence, we carried out a series in vivo and in vitro studies, and results showed that the EGFR activation mediated pancreatic cancer initiation was partly HSF1 dependent." (PMID 33422093, 2021). "In addition, targeted therapies that the United States Food and Drug Administration (FDA) has approved as treatments for pancreatic cancer include epidermal growth factor receptor (EGFR/ErbB) inhibitors and tyrosine kinase inhibitor (TKI)." (PMID 34833063, 2021). "In addition, we further evaluated the proliferation and metastasis of pancreatic cancer cells treated with 6-P after adding EGFR plasmid to upregulate EGFR expression." (PMID 34376189, 2021). "As ADM is a necessary process for the malignant transformation of pancreatic acinar cells (into pancreatic precancerous lesions PanINs), it is reasonable to believe that EGFR and its downstream pathways play a critical role in the initiation of pancreatic cancer." (PMID 33422093, 2021). "The results of future clinical trials using more reliable biomarkers for the response to therapy with anti-EGFR mAbs may lead to the approval of anti-EGFR mAbs in a more specific population of pancreatic cancer patients." (PMID 33917882, 2021). "AREG reacts with cancer cells and results in the activation of EGFR in pancreatic cancer." (PMID 34326696, 2021). "The results revealed Erlotinib and 6-P had synergistic effects to exert inhibition on proliferation and metastasis of pancreatic cancer cells, which could be rescued by upregulation of EGFR expression." (PMID 34376189, 2021). "EGFR expression was observed in 62–69% of pancreatic cancer patients with IHC analysis." (PMID 36405499, 2021). "To determine whether NETs mediated migration and invasion of pancreatic cancer cells are EGFR/ERK dependent, we examined the effects of EGFR and ERK inhibitors on pancreatic cancer cells after treatment with CM‐NETs." (PMID 33955688, 2021). "Results showed that EGFR is significantly associated with the prognosis of CD8 + T-cell-enriched pancreatic cancers and not -decreased pancreatic cancers." (PMID 34479614, 2021). "Indeed, GSEA analysis based on above TCGA datasets also revealed the core role of EGFR in pancreatic cancer related pathways and other well-known tumorigenesis related pathways." (PMID 33422093, 2021). "Therefore, EGFR is a good target for the imaging diagnosis of early pancreatic cancer with positron emission tomography (PET)." (PMID 35056963, 2021). "Using a KC transgenic mouse model, which can mimic the whole process of the initiation and progression of pancreatic cancer, especially from normal acinar cells to ADM and subsequent PanINs, we demonstrated that the EGFR-HSF1axis promoted the initiation of pancreatic cancer." (PMID 33422093, 2021). "Moreover, increased SOX9 and TSPAN8 levels were shown to correlate in human pancreatic cancer specimens and downregulated in vitro by EGFR tyrosine kinase inhibitors." (PMID 34163029, 2021). "Combinations being explored include cetuximab plus MRTX849, pembrolizumab, and afatinib in the treatment of KRAS G12C-mutant pancreatic cancer (NCT03785249), as well as cetuximab plus trastuzumab and SNK01 for the treatment of advanced, EGFR-positive pancreatic cancer (NCT04464967)." (PMID 33546207, 2021). "Cetuximab, an anti-EGFR monoclonal antibody, has been approved for the treatment of colorectal cancer, as well as squamous cell carcinoma of the head and neck, and is in trials for the treatment of advanced pancreatic cancer." (PMID 33546207, 2021).